CD4 (CD4 molecule)
Diseases named in the same sentence as CD4 in open-access papers (continued):
Sharing a sentence is not in itself a finding about the gene and the disease.
Immunodeficiency (continued). "Collectively, we showed that both CD4+and CD8+ T-cells isolated from chronic SCI mice have defects in cytokine production, which may contribute to the chronic SCI induced immunodeficiency." (PMID 24690491, 2014). "The maintenance of CD4+ T-cells and CD8+ T-cells numbers characterizes the efficacy of HAART, which inhibits viral replication, slows the progression of immunodeficiency, and therefore restores immunity, increasing the quality of life of HIV-1-infected individuals." (PMID 24719500, 2014). "By contrast, B6 congenic strains that lacked most or all T-cell subsets (nude, severe combined immunodeficiency, or Rag1tm1Mom) developed tumors while those lacking only CD4+ or CD8+ T-cells or only B-cells did not develop tumors." (PMID 25474466, 2014). "Although our patient’s history appeared to be negative for immunodeficiency before his thymectomy, we advise that patients with thymoma should receive an immune work-up including CD4+ and CD8+ counts prior to treatment." (PMID 25528459, 2014). "Controllers had stable CD4+ and B-cell counts, and did not display symptoms of immunodeficiency during the observation period." (PMID 24928910, 2014). "It is noted that among the HIV-uninfected, the HIV-egg+IgEhi subgroup had the lowest median CD4+ cells though still just above the threshold for onset of immunodeficiency (0.5 cells/ml), however this was not statistically significant (p = 0.26)." (PMID 25209883, 2014). "This work suggests that contraceptive doses of MPA but not NET-A or physiological doses of progesterone could potentially accelerate depletion of CD4+ T-cells in a GR-dependent fashion in HIV-1 positive women, thereby contributing to immunodeficiency." (PMID 23658782, 2013). "Our data suggest that crosslinking of CD4 by gp120 and anti-gp120 antibodies may shutdown T-cell activation also during immune responses in HIV-infected patients, thus contributing to immunodeficiency." (PMID 23317458, 2013). "Investigation of CD4+ and CD8+ T-cell counts revealed significantly fewer CD4+ T-cells in TB and HIV co-infected patients compared with single-infected subjects with either TB or HIV alone, suggesting a more advanced immunodeficiency in co-infected patients." (PMID 29043167, 2013). "In the course of this study, we noted a markedly decreased expression of the chemokine receptor CXCR4 at the surface of CD4+ T cells from ICL patients, suggesting that impaired CXCR4-dependent cell trafficking may contribute to the immunodeficiency." (PMID 23383227, 2013). "Immunologic failure is a rapid, serial rate of decline to the cut-off values for severe immunodeficiency state for age or below; or a fall in CD4 by 50% from the recorded peak in the absence of a concurrent illness." (PMID 22916836, 2012). "For example, the defect of MHC class II that leads to combined immunodeficiency with defective CD4+ T-cell development and a lack of T-helper-cell-dependent antibody production by B cells, was not reported to cause Omenn phenotype so far." (PMID 23243423, 2012). "The immunodeficiency subtype is frequently observed in the setting of human immunodeficiency virus (HIV) infection and, unlike other HIV-related lymphomas, is frequently noted in patients with CD4 counts exceeding 200 cells/μL." (PMID 23049564, 2012). "This is the first report of HIV negative patients with lymphocytopenia and CD4 lymphocytopenia with clinical immunodeficiency who did improve their T CD4 count, their lymphocytes count and their illness with anti-human herpes virus treatment." (PMID 24893304, 2012). "Together with the decline in CD4+ T cell numbers, the downregulation of TLR8, IL-8 and HLA-DOA expressed on macrophages/dendritic cells and B cells, respectively, suggests generalized immune dysfunction that can in due course lead to immune exhaustion." (PMID 22511950, 2012).
Immunodeficiency (continued). "Immunodeficiencies with less prominent autoimmune manifestations include common variable immunodeficiency, Good syndrome, hyper-IgM syndrome, WAS, and idiopathic CD4+ lymphocytopenia." (PMID 21914180, 2011). "Adjustment for HIV infection and decline in CD4 count did not alter the associations meaningfully, suggesting that there is only a small confounding effect of HIV and its associated immune deficiency on the risk of HPV in cervical adenocarcinoma." (PMID 21702999, 2011). "In contrast to TST, sensitivity of T-SPOT.TB was independent of the level of immunodeficiency, although a trend towards higher number of spot forming units with increasing CD4 cell count was observed in patients with a positive T-SPOT.TB." (PMID 22085801, 2011). "Major histocompatability complex deficiencies also cause immunodeficiency; MHC II is required to present antigen to CD4 lymphocytes, its absence results in lack of CD4 activation." (PMID 20465788, 2010). "Interestingly, CD4-independent strains tend to be neutralization-sensitive and have been isolated from SIV-infected animals with advanced immunodeficiency, from immune-privileged areas such as the CNS, or upon passage under selection in cell culture." (PMID 21203482, 2010). "It is worth noting that all selected patients were matched to have conserved levels of CD4 T cells, so the differences observed were not attributable to distinct degrees of immunodeficiency." (PMID 20195543, 2010). "Based upon these data, the authors have explored the intracellular events in the CD8+ target cells, following co-culture with CD4+CD25+ Treg cells, for a clearer understanding of what may contribute to CD8+ immune dysfunction." (PMID 21092106, 2010). "Nevertheless, these data are consistent with consideration of TB as an indicator of a level of immunodeficiency for which initiation or change of ART is indicated in the absence of CD4 count." (PMID 19383122, 2009). "Increased immunodeficiency would result in reduced trafficking of CD4+ T cells into the CNS, so these cells would no longer be present to amplify virus from local CNS tissue, consistent with the reduced pleocytosis in this group." (PMID 19390619, 2009). "By contrast, increased CTLA-4 expression on HIV-specific CD4 (but not CD8) T cells is strongly associated with disease progression and reversible immune dysfunction in HIV-infected patients." (PMID 19247441, 2009). "Additionally, one patient with combined immunodeficiency had relatively low levels of antibodies (IgG titre of 4700) and did not develop detectable CD4 T-cells response." (PMID 41280926, 2025). "Similarly, an increased ratio of Tregs to effector T cells and altered CD4+ and CD8+ T cell effector functions could contribute to immunodeficiency disease." (PMID 40627451, 2025). "While the correlation between total HIV-1 DNA levels and CD4 T cells was not statistically significant in participants with severe immunodeficiency (CD4 T cells < 200), it's worth noting that among the five individuals in this category, four showed elevated levels of total HIV-1 DNA." (PMID 38601701, 2024). "Indeed, nine participants had a CD4+ T-cell count <500 cells/μl, of whom one < 250 cells/μl, but none of them showed clinical signs of cellular immunodeficiency." (PMID 38788210, 2024). "Additionally, immune dysfunction (CD4+ < 500 cells/μl) exhibited negative correlations with BMI, PNI, TP, ALB, PA, and TRF." (PMID 39086487, 2024). "In terms of limitations, first our results are applicable to PWH with well-controlled viremia on ART without severe immune deficiency and may not apply similarly to PWH with a much lower CD4 count in spite of ART or those not on ART." (PMID 37166335, 2023). "Indeed, a growing number of studies suggest that lymphocytopenia occurs in patients with CKD or ERSD, in part as immune dysfunction induced by T cell-mediated changes in the absolute number of CD4+ and CD8+ T cells, even the absolute number of CD4+ and CD8+ in renal fibrosis." (PMID 36629622, 2023).
Immunodeficiency (continued). "Compared with IPF patients, SSc-ILD patients had more Th17 and Th22 cells in circulation, while RA-ILD patients had more B cells and CD4+ T cells in lung tissue than IPF patients, implying that CTD-ILD patients may be more prone to immune dysfunction than IPF patients." (PMID 37307262, 2023). "Therefore, both C. cellulosae ESAs and TPx could induce the increase in the CD4+/CD8+ T-cell ratio in piglet PBMCs, leading to T cells imbalance and immune dysfunction." (PMID 36466695, 2022). "Finally, as the claim data did not include clinical data in addition to laboratory test results, we were unable to extract data on CD4 count and HIV viral load, which could have helped predict the level of immune dysfunction." (PMID 35705675, 2022). "However, some patients still fail to attain normal CD4+ T cell counts; this group of patients are called immune non-responders (INRs), and these patients show severe immune dysfunction." (PMID 36325329, 2022). "CD4+ T-cell percentage improved over the first 6 months of ART, increasing a mean of 1.6% per month, and then stabilized, such that the proportion with severe immunodeficiency decreased from 57.1% at ART initiation to 7.7% at 6 months on ART, and then remained at 0 to 6.6% until 36 months." (PMID 34261465, 2021). "A more comprehensive assessment is also important as some SARS-CoV-2-specific CD4 T cells may not express the traditional surface markers or produce typical cytokines as a result of this immune dysfunction." (PMID 34270631, 2021). "Although the reason for this is not yet known, immune system disorders in NALFD may be an important cause, such as a decrease in CD4 + T cells and abnormal macrophage function." (PMID 34761514, 2021). "By analyzing a selected group with a high probability of the endpoint as well as a presumed high level of functional immunodeficiency, WHO stage and CD4+ cell count might not further discriminate risk." (PMID 32130279, 2020). "Depletion of the entire CD4+ T cell population would leave patients severely immunocompromised; short-term immunodeficiency can be clinically managed as shown, for example, for patients with SCID (severe combined immunodeficiency), a severe dysfunction of B cells, T cells or both." (PMID 32918599, 2020). "Except for one patient who had human immunodeficiency virus (HIV) with low cluster of differentiation 4 (CD4) count, none of our bacteremic patients had immunodeficiency, indwelling central line, or sickle cell disease; however, two of them had a history of asthma and prematurity." (PMID 32582483, 2020). "While CD4 counts rise fairly fast on HIV medications, the CD4/CD8 ratio does not rise or at best rises quite slowly and new evidence suggests this may be a marker for continuing HIV related immune dysfunction even when on ART." (PMID 32442166, 2020). "For instance, IL2 promotes the development of CD4+CD25+FoxP3+ Tregs, that represent an immunomodulatory T cell specialized subset able to neutralize the development of immune-mediated damage and to promote repair and regeneration of affected target-organs in systemic immune diseases." (PMID 33324641, 2020). "Third, we found that around 20% of the ALHIV did not have documented investigation/test results for CD4 cell count, hepatitis B, hepatitis C and haemoglobin at enrolment indicating missed opportunities for identifying cases with severe immunodeficiency and/or co-morbidities early." (PMID 31364536, 2019). "Therefore, analysis of naïve CD4 and CD8 cells provide a picture of the immune reconstitution process in A-T patients and other patients with chromosomal instability and/or immunodeficiency syndromes and seems to be relevant markers for the measure of quality of the HSCT." (PMID 31849966, 2019).
Immunodeficiency (continued). "The immune dysfunction is not probably due to impaired T-cell function, since neither CD4+ T-cell dependent IFNγ producing cell number nor IL10 producing regulatory T-cells resulted different outcomes in response to PMA-Ionomycin and PHA-LPS stimulation, respectively." (PMID 28170444, 2017). "CD4/CD8 ratio could be an important marker of a patient’s net status of immunodeficiency during RTX, since inverted CD4/CD8 ratio is a common surrogate marker of immunosenescence of impaired responses to vaccination and infections due to the loss of repertoire diversity." (PMID 27688979, 2016). "In this study, we report that the functional compartments of CD4+ and CD8+ T cells are differentially regulated by MSCs, which may condition the outcome of MSC cell therapy in immune disorders with distinctive distribution of T cells among activation/differentiation compartments." (PMID 25559824, 2015). "Although there are limited research findings for severe CFS/ME patients, the differences in NK cells, CD4+T and CD8+T cells between severity groups, found in this research, suggest that immune dysfunction in CFS/ME may be related to clinical symptoms and hence severity." (PMID 26032326, 2015). "Early ART initiation may contribute to more rapid and robust CD4/CD8 ratio normalization, and the CD4/CD8 ratio may be a useful clinical endpoint to be used in evaluating novel therapies for ongoing immune dysfunction during treated infection and for HIV eradication." (PMID 24831517, 2014). "A possible explanation for this might be that the degree of immunodeficiency in participants who had no increase in the CD4+ cell count was too high to show any significant gain in physical functioning from the absence of the NCDs." (PMID 24711874, 2013). "Moreover, lack of information on CD4 count of HIV-infected children is another limitation of this review, which makes it difficult to determine the extent of immune deficiency in the HIV-infected children." (PMID 24288943, 2013). "Furthermore, CD4 T cells were shown to contribute to the destruction of the splenic architecture following LCMV infection by a CD4 T cell derived TNF and IFNγ-dependent mechanism, leading to subsequent immunodeficiency." (PMID 23717308, 2013). "Despite limited follow-up time and difficult to diagnose HIV infection in its early stage ("window period"), the study has shown that the outcome in burn patients is dependent upon multiple variables and not the underlying immunodeficiency (i.e. HIV seropositivity and CD4+ cell count) alone." (PMID 21658212, 2011). "APC dysfunction in HIV-infected individuals could accelerate or exacerbate CD4+ T cell dysfunction and may contribute to increased levels of immunodeficiency seen in some patients regardless of their CD4+ T cell numbers." (PMID 20209134, 2010). "Consistent with the higher vRNA levels in CD4+ CM T cells of coinfected animals, 4 out of the 6 of these monkeys also had losses to abnormal levels (<10%) of the CD4+CD29+ subset of memory T-cells in peripheral blood, which is an early sign of immune dysfunction in lentivirus-infected-macaques." (PMID 18648516, 2008). "Additionally, miR-326 and CD4+CD200+ cells, as well as miR-486 and sCD200R, exhibited significant differences in correlation coefficient values, suggesting possible changes in pathways regulating the immune response that depend on the CD200/CD200R axis in different types of immunodeficiencies." (PMID 41148792, 2025). "BALB/c recipients with GVHD had very low to no detectable B cells, CD4 T cells, or CD8 T cells in peripheral blood as compared with transplanted control mice without GVHD, suggesting that loss of MCMV control in recipient mice with GVHD was caused by profound GVHD-induced immunodeficiency." (PMID 36719764, 2023).
Immunodeficiency (continued). "Furthermore, with the success of modern cART and viral suppression, the absolute CD4 count and HIV viral load may not accurately reflect the risks of patients because immune dysfunction persists despite normalization of the CD4 count." (PMID 35873145, 2022). "However, since anti-CD4 CAR T cells can persist over months or years, patients might suffer from immunodeficiency due to a severe side-effect: the prolonged elimination not only of malignant but also healthy CD4+ T cells." (PMID 32679920, 2020). "However, none of these genetic defects are specific for the CD4 T-cell lineage, and Idiopathic CD4 lymphopenia patients typically display additional clinical and immunological features in common with other combined immunodeficiencies." (PMID 31781092, 2019). "It is possible that in children currently experiencing an episode of OM, the reduced IFNγ+ CD4+ T cell response to NTHi challenge is a reflection of lymphocyte exhaustion (or deployment of these antigen-reactive cells to the ear) rather than an inherent cell-mediated immunodeficiency." (PMID 29621281, 2018). "The increased amount of CD4+CD28− T lymphocytes in patients with MHE indicates stronger immune dysfunctions than in patients without MHE, with persistent immune activation, increased production of TNFα, IFNγ and of molecules which may damage endothelial cells and tissues." (PMID 28751644, 2017). "Because the CD4 count was low in both patients at the time of relapse in spite of undetectable HIV RNA levels in the serum, the occurrence of HIV-MCD flares may be dependent on HIV-induced immunodeficiency, and controlling HIV infection is a major factor in patients with HIV-MCD." (PMID 24438824, 2014). "Although immune dysfunction following mucosal CD4+ T cell loss is well described, it is not known whether HIV can alter mucosal function and epithelial integrity prior to and independent of CD4+ T cell depletion in vivo." (PMID 25166758, 2014). "Because of the cross-sectional nature of this study, it is not possible to determine whether the association between CD4+ NKT loss and increased immune activation indicated a causal relationship, or reflected the effect of advanced immunodeficiency in chronic SIV infection." (PMID 23028326, 2012). "Immunological assessments revealed profound immunosuppression, marked by decreased CD4+ T cells (0.037 x 109/L), alongside mildly elevated IgG levels (16.701 g/L), reflecting both HIV-related immunodeficiency and non-adherence to antiretroviral therapy (ART)." (PMID 39421098, 2024). "We show a lack of naïve CD4+ T cells and very abnormal TCR repertoires, in line with their immunodeficiency due to failure of thymus development, as previously reported." (PMID 37689091, 2023). "Changes verified for the CD4+/CD8+ ratio are in line with the behavior of the other selected immune markers and did not point out any signal of immunodeficiency or immune improvement." (PMID 35743844, 2022). "Compared to 7% immunodeficiency among controls, 56% of patients on ART and 65.5% of those not on ART had a CD4 count < 350 cells/mm3 (p < 0.001)." (PMID 36483323, 2022). "Immunological abnormalities such as reduced CD4+ T cells, reduced CD4:CD8 ratio, or altered immunoglobulin levels are described and can often be detected even in patients without clinical immunodeficiency." (PMID 34422726, 2021). "Furthermore, a low CD4 nadir has been linked with gut microbiome dysbiosis in HIV-infected individuals, and an association between HIV-associated gut microbiome dysbiosis and metabolic syndrome was significantly stronger in individuals with past severe immunodeficiency compared to those without." (PMID 34006628, 2021). "Data have shown that immune dysfunction and chronic inflammation are not completely resolved during ART despite suppression of viral replication and restoration of CD4 T cell count in peripheral blood." (PMID 33923310, 2021).